INS (insulin)
Diseases named in the same sentence as INS in open-access papers (continued):
Sharing a sentence is not in itself a finding about the gene and the disease.
diabetes (continued). "Hyperglycemia is the hallmark of type 1 diabetes mellitus (T1DM), T2DM, and GDM, resulting from a decline of insulin supply that is insufficient to meet tissue demands for normal blood glucose regulation and/or insensitivity of insulin towards insulin receptors." (PMID 30563117, 2018). "27% of T2DM patients managed their diabetes with OADs and insulin." (PMID 29476413, 2018). "Lack of production of enough insulin by pancreas or responding correctly to insulin production by body cells are two main causes of diabetes." (PMID 30581791, 2018). "When the LAG was combined with a four times increased insulin dose, the glucose lowering effect of insulin was prolonged, which could potentially be beneficial in diabetes treatment." (PMID 29558502, 2018). "Pharmacodynamics of insulin in rats with alloxan-induced diabetes." (PMID 29688087, 2018). "In our previous study, we reported that both a lower insulingenic index, which exhibits decreased early-phase insulin secretion and insulin therapy during pregnancy are independent predictors for abnormal glucose tolerance, including both prediabetes and diabetes, in the early postpartum period." (PMID 29310607, 2018). "Since obese individuals who are at risk for Type 2 diabetes mellitus may utilize a VLC diet to lose weight, it is important to understand the effect of VLC diets on hepatic response to insulin." (PMID 31061673, 2018). "Similarly, several important changes in diabetes management have been introduced over the study period such as the introduction of novel insulin formulations, widespread adoption of intensive insulin treatment schemes and revision of education systems." (PMID 29478098, 2018). "Indeed, it has been demonstrated that weight gain in patients with diabetes is related to many factors such as over-replacement of insulin, increased calorie intake, as an adaptive response to hypoglycaemia, and insulin resistance." (PMID 30093885, 2018). "However, type II diabetes (T2DM), accounting for the majority of diabetes cases around the world, stems from either insulin resistance or insufficient insulin production." (PMID 30065848, 2018). "The highest insulin secretion in MKR male mice suggested that males were affected by a more severe insulin-resistance that could evolve towards an overt diabetes." (PMID 29662006, 2018). "Akt has many activities besides regulating glucose metabolism and can become resistant with long‐term diabetes exposure and insulin resistance that normally occurs via Akt may shift to the MAPK pathway." (PMID 30338211, 2018). "Diabetes mellitus is a huge and growing global health problem which demands modern therapy involving greater and earlier use of intensive insulin regimens in order to achieve better control of blood glucose levels and reduce the long-term risks associated with the condition." (PMID 30116742, 2018). "In relation to time, it may be important to identify the role of other team members in delivering insulin support such as primary care nurses or diabetes specialist nurses supporting the primary care team." (PMID 29788908, 2018). "Given that estrogen and insulin signaling actions share common regulatory pathways for maintenance of cardiomyocyte function, involvement of sex steroids in mediating differential cardiac effects of diabetes in males and females is plausible." (PMID 29402990, 2018). "Of the six components of this score, insulin/sugar ratio is related to diabetes, HDL is related to lipid metabolism, platelet count is associated with severity of fibrosis, and lymphocyte/neutrophil ratio is associated with clinical outcomes in many cancers, including HCC." (PMID 29872158, 2018). "Additionally, there was a history of gestational diabetes in the patient’s mother and diabetes requiring insulin therapy in a maternal uncle." (PMID 28766502, 2018).
diabetes (continued). "Continuous subcutaneous insulin infusion (CSII) therapy has been used in the treatment of type 1 diabetes mellitus (T1DM) since the 1970’s and is increasingly used as an alternative to multiple daily insulin (MDI) therapy as pumps have become more widely available." (PMID 29537377, 2018). "Further studies are required to isolate the phytoconstituents responsible for the antidiabetic activity and to elucidate their mechanism of action including effects on various specific markers of Diabetes mellitus including insulin and glycated hemoglobin levels." (PMID 30545352, 2018). "Importantly, Ide, Ppp1r3c, and Bad are located in Niddm1b, a diabetes susceptibility QTL which primarily affects insulin action and insulin-stimulated glucose transport." (PMID 30687391, 2018). "The Study of Osteoporotic Fractures revealed an increased risk of falls in women with diabetes, especially in those treated with insulin, who had more than double the risk of having multiple falls than women without diabetes." (PMID 29721333, 2018). "Diabetes mellitus (DM) is a chronic disease caused by lack of insulin secretion or lower biological effects of insulin." (PMID 29437903, 2018). "These analyses revealed that fasted miR-29a/b1−/− mice exhibit hyperglycemia, probably because of their reduced serum insulin concentration and the up-regulation of the gluconeogenic pathway in the liver, two features frequently present in diabetes mellitus patients." (PMID 30346946, 2018). "However, more research is needed to confirm our findings and to explore the role of insulin signaling in breast cancer initiation and/or promotion in patients with diabetes, especially among those using insulin or insulin analogues." (PMID 29486734, 2018). "Insulin degludec (IDeg) and insulin glargine (IGlar) are both proved to be effective in diabetes." (PMID 29721018, 2018). "Administration of methyl-GBB (4-ethyl(dimethyl)ammonio-butanoate) resulted in decreased acylcarnitine levels, which, in turn, improved insulin sensitivity and significantly reduced blood glucose and insulin levels in mice with impaired insulin sensitivity and diabetes." (PMID 29549241, 2018). "However, in all cases, insulin secretion was impaired to an extent that resulted in increased fasting glucose levels or diabetes." (PMID 30541568, 2018). "For many years, insulin has been a vital part of diabetes treatment." (PMID 29595915, 2018). "It is possible that insulin treatment reflects a more prolonged and advanced stage of diabetes." (PMID 29402330, 2018). "Interestingly, diabetes patients display deficits in insulin signalling that is likely to be related to observed reduced AKT signalling." (PMID 29891871, 2018). "Ten studies specified eligibility criteria regarding the risk of diabetes: postpartum glucose intolerance, overweight or obesity, low level of physical activity, altered lipid profile, high waist circumference, family history of diabetes, use of insulin during pregnancy or hypertension." (PMID 30344509, 2018). "The odds of developing IGT or diabetes increased to nearly fourfold when women needed insulin for the control of GDM during pregnancy (OR 3.8, 95% CI 0.81–18.3, P = 0.08) and to nearly one-and-a-half-fold when they have positive family history of T2DM (OR 1.2, 95% CI 0.74–2.09, P = 0.40)." (PMID 30186874, 2018). "Also in people with diabetes, Cmax has been reported to be 28% higher and occur more than twice as fast upon injection of human insulin into the abdomen compared to the thigh." (PMID 30116732, 2018). "Accordingly, it is not surprising that insulin-resistant muscle represents a major challenge to maintaining healthy glycaemia and thus is a risk factor for developing diabetes." (PMID 30013070, 2018).
diabetes (continued). "The result of this retrospective analysis shows that hybrid closed‐loop users with well‐controlled Type 1 diabetes have higher bolusing frequency and total amount of self‐administered bolus insulin relative to total daytime insulin, compared with those with suboptimally controlled diabetes." (PMID 28755444, 2018). "The mechanisms by which CSII achieves protracted glycemic remission in T2D may be the improvement in beta-cell function and insulin resistance, and, may partially, because the positive attitudes towards diabetes by CSII therapy." (PMID 29946148, 2018). "He had diabetes diagnosed at the age of 2 years and was initially treated with insulin." (PMID 29450569, 2018). "Pancreatic anomaly termed agenesis can occur due to disrupted IPF gene activity and heterozygous IPF mutations can cause defective insulin secretion thus MODY 4 diabetes, while as, homozygous mutation resulting in permanent neonatal diabetes (PND) and pancreatic exocrine insufficiency." (PMID 29867778, 2018). "Fasting plasma levels of glycated hemoglobin, leptin, pro-insulin and retinol binding protein 4 differed between impaired fasting glucose/impaired glucose tolerance and normal subjects group and between newly detected diabetes and normal subjects group." (PMID 29610560, 2018). "A study determining whether exposure to experimental hyperglycemia (via infusion) or rapid normalization of hyperglycemia in diabetes patients (via insulin or sodium-glucose cotransport inhibitors drugs) can directly influence exercise adaptations is needed." (PMID 30061841, 2018). "Furthermore, diabetes can result from monogenic defects in β cell function, diseases of the exocrine pancreas, endocrinopathies due to hormones antagonizing insulin, drug or chemically induced." (PMID 29534427, 2018). "However, duration of diabetes, secondary education, previous diabetes education, having a confidant for diabetes, insulin use, self-measurement of blood glucose were independently positively associated with DSMES Score." (PMID 30214472, 2018). "The second case involves a 30 year old female with diabetes since age 13, a family history of paternally-transmitted early-onset diabetes, a BMI of 26.32 kg/m2, no history of diabetic ketoacidosis and treatment with long-acting insulin." (PMID 29764441, 2018). "Our objectives were to evaluate treatment adherence to insulin, emotional distress (using the Problem Areas in Diabetes Questionnaire, PAID), trust in physician, and to examine associations between them among Lebanese patients with diabetes." (PMID 29520741, 2018). "Therefore, the aim of the present study was to investigate the association of serum insulin levels and IR with UGE in subjects with glucose abnormalities, including prediabetes and diabetes." (PMID 30519194, 2018). "This study was conducted to reveal the relationship between diabetes-induced oxidative stress and tissue inflammation with changes in main enzymatic antioxidants (cat, sod, gpx, and gst) and the components of the insulin signaling pathway (insulin Rβ, irs-1, pi3k, akt, mtor) in kidney tissues." (PMID 30602713, 2018). "The basal-bolus insulin regimen is the starting treatment for individuals with type 1 (DM1) diabetes, whereas in patients with diabetes type 2 (DM2), it is the final step when an optimal glycemic control is not obtained with other antidiabetic drugs (OADs), or these are contraindicated." (PMID 30918874, 2018). "As described in the introduction, we hypothesized that brain Hes3 expression would be altered in mouse models of diabetes, in which insulin signaling is perturbed." (PMID 30054579, 2018). "Thiazolidinediones (TZDs) are a class of medicines commonly used alongside diet and exercise as therapeutic agents for the treatment of patients with type 2 diabetes mellitus, a disease in which defects in both peripheral insulin resistance and pancreatic beta cell insulin secretion coexist." (PMID 30123711, 2018).
diabetes (continued). "Furthermore, C3G treatment resulted in increased insulin secretion compared with the control diabetic group, and is a potential phytotherapeutic agent for the prevention of diabetes." (PMID 30564116, 2018). "It is, therefore, important to identify molecular mechanisms by which diabetes mellitus may affect the brain, either directly via alterations in the levels of circulating glucose and insulin or indirectly through effects on the immune/inflammatory system." (PMID 30054579, 2018). "Therefore, breath acetone testing plays an important role in monitoring the diabetes as well to control the intake of insulin for diabetics patients." (PMID 29979737, 2018). "At the end of the extension phase, the following efficacy outcomes were assessed: change from BL in glycemic control (HbA1c, FPG, and 8-point SMPG profiles), mean insulin dose (basal and mealtime), and score on the Diabetes Treatment Satisfaction Questionnaire (DTSQ)." (PMID 29619381, 2018). "These genes were annotated with diabetes and insulin processing related GO terms and pathways." (PMID 30451954, 2018). "Increased skeletal muscle diacylglycerol and CER levels have been linked to dysregulation of insulin signaling and insulin resistance, and it is hypothesized that CER may be particularly important in the pathogenesis of diabetes." (PMID 30322152, 2018). "A potential confounder to consider is that having the option of insulin restriction for the purpose of weight control could result in reduction of other purging behaviours in individuals with diabetes." (PMID 29744106, 2018). "The development of diabetes may occur as a result of insulin secretion and/or signaling deregulation by insulin receptors (IR)." (PMID 30558294, 2018). "However, in murine models of diabetes and people with diabetes, impaired insulin-stimulated blood flow and NO bioavailability have been demonstrated." (PMID 30563079, 2018). "The ability to obtain a large number of mature insulin-producing cells from hESC/iPSC could provide unlimited supplies of surrogate β cells to replace damaged cells in patients with diabetes." (PMID 30594258, 2018). "However, lipohypertrophy has been a recognized complication of insulin therapy for many years, yet researches showed that its prevalence in insulin-injecting patients with diabetes remains greater than 50%." (PMID 30116742, 2018). "Results suggest that EAF isolated from stevia leaves is a potential therapy for treating type 2 diabetes mellitus by stimulating insulin secretion only in high glucose concentrations, enhancing parasympathetic signal transduction and inhibiting sympathetic signal transduction in beta cells." (PMID 29853880, 2018). "However, for previously diagnosed and newly diagnosed diabetes participants, the situation became complicated as the relationship between insulin and HOMA-IR levels and age is related to gender." (PMID 30211231, 2018). "Diabetes mellitus (DM) is a group of metabolic diseases characterized by hyperglycemia [fasting plasma glucose ≥126 mg/dl (7.0 mmol/l) or 2-h plasma glucose ≥200 mg/dl (11.1 mmol/l)] resulting from defects in insulin secretion, insulin action, or both." (PMID 29324896, 2018). "Insulin analogs were developed in order to provide a better glycemic control to diabetes patients." (PMID 29615978, 2018). "Although we excluded all T2DM patients, who received insulin as their first anti-diabetes drug from our study cohort, some patients with T1DM might still be misclassified as having T2DM." (PMID 29855473, 2018). "Furthermore, half (3/6) of the buffer-treated SOCS1-tg mice developed diabetes upon infection with CVB1, with a loss of the insulin-positive beta cells and damage to the exocrine pancreas." (PMID 29151123, 2018).
diabetes (continued). "FEEHD is arbitrarily defined by the following criteria: a hypoglycemic event (blood glucose below 70 mg/dl) in patients with diabetes who take insulin or sulfonylurea, or both, who fast overnight for lab tests, and who commute to the laboratory facility while fasting." (PMID 30473710, 2018). "Some respondents may have had difficulty in reporting events that happened in the past (e.g., duration of insulin therapy, diagnosis of diabetes, etc.), so the potential for recall bias must also be considered as a limitation." (PMID 30555274, 2018). "Thus, the absence of encapsulated cells injection treatment to prevent diabetes complications is also influenced by the depletion of insulin secretion." (PMID 29868580, 2018). "In addition to insulin therapy, diabetes treatments include inhibiting oligo- and disaccharide degradation, reducing insulin demand, stimulating endogenous insulin secretion, and enhancing insulin action at target tissues." (PMID 29614722, 2018). "Therefore, C-peptide is the best measure of endogenous insulin secretion and is widely used in the clinical management of patients with diabetes." (PMID 29401509, 2018). "The potential for a drop in tear levels of insulin in diabetes and a corresponding increase in nuclear Hybrid-R may contribute to abnormal corneal epithelial homeostasis and metabolism." (PMID 29531349, 2018). "With respect to diabetes, vitamin D is involved in the secretion and action of insulin and may influence chronic low-grade inflammation and angiogenesis." (PMID 29530048, 2018). "Diabetes mellitus (DM) is a metabolic disorder of multiple etiologies characterized by increased level of glucose in the blood with disturbances of carbohydrate, fat and protein metabolism resulting from defects in insulin secretion, insulin action, or both." (PMID 30477553, 2018). "The adolescents with diabetes showed the higher percentage of using special equipment due to the disease (97.7%; n=42) (e.g., tolls related to the monitoring of blood glucose and the intake of insulin)." (PMID 30643522, 2018). "In the only other study to examine symptom responses to glycemic control, postprandial fullness was identical in year 13/14 of the Epidemiology of Diabetes Interventions and Complications study in patients initially randomized to intensive versus conventional insulin therapies in DCCT." (PMID 29652893, 2018). "The action of insulin in liver is to suppress hepatic glucose production and lipolysis-induced lipid accumulation in the liver is shown to attenuate insulin sensitivity and increase hepatic glucose production, responsible for hyperglycemia during fasting in diabetes." (PMID 30154727, 2018). "T2DM is the most common form of diabetes and is characterized by disorders of insulin action and insulin secretion, either of which may be the predominant feature." (PMID 29884161, 2018). "Diabetes mellitus, a metabolic disease characterized by chronic hyperglycemia, with disturbances in the metabolism of carbohydrates, proteins, and fats, is due to defects in insulin action or insulin secretion or both." (PMID 29435415, 2018). "Weight loss is difficult to maintain and attempts to lose weight may be undermined by some diabetes treatments such as sulfonylureas, thiazolidinediones and insulin." (PMID 28501906, 2018). "Mortality is even higher when the diabetes treatment strategy included insulin." (PMID 30497472, 2018). "To extrapolate accurately the impact of interventions on the risk of diabetes incidence, we investigated the size and shape of the associations of fasting plasma glucose (FPG), 2 h post-load glucose (2hPG), HbA1c, fasting insulin and HOMA-IR with incident type 2 diabetes mellitus." (PMID 29018885, 2018). "Postprandial non-esterified fatty acid (NEFA) and triglyceride (TG) responses are increased in subjects with type 2 diabetes mellitus (T2DM) and may impair insulin action and increase risk of cardiovascular disease and death." (PMID 30591062, 2018).